ICAM1 (intercellular adhesion molecule 1)
Diseases named in the same sentence as ICAM1 in open-access papers (continued):
Sharing a sentence is not in itself a finding about the gene and the disease.
uveitis (15 papers, 2011 to 2025). An inflammatory process affecting a part of or the entire uvea. "ICAM-1 has been implicated in the development of the most common infectious form of uveitis, caused by Toxoplasma gondii and often referred to as ocular toxoplasmosis or toxoplasmic retinochoroiditis." (PMID 37237555, 2023). "Nevertheless, genetic studies have indicated that ICAM-1 (rs5498) is a susceptible locus for the development of BD-associated uveitis." (PMID 35008929, 2022). "It is widely accepted that multiple cytokines, chemokines, and adhesion molecules, such as TNF-α, MCP-1, RANTES, fractalkine, iNOS, and ICAM-1, are implicated in the pathogenesis of uveitis." (PMID 25147441, 2014). "In addition to uveitis, proliferative vitreoretinopathy, diabetic retinopathy, and macular pucker are all associated with ICAM-1 expression." (PMID 25032222, 2014). "ICAM-1, an inducible cell transmembrane glycoprotein, acts as a key component in inflammatory response for recruiting leukocytes to the sites of inflammation and is implicated in the pathogenesis of numerous inflammatory diseases such as rheumatoid arthritis, uveitis, and atherosclerosis." (PMID 23401649, 2013). "We selected the chemokine/chemokine receptor genes IL10 receptor (IL10R), IL15, IL15 receptor α (IL15RA) and the adhesion gene ICAM1 that were believed to be the common biomarkers of many forms of uveitis." (PMID 36163311, 2022). "There is direct evidence of VCAM-1 as well as ICAM-1/LFA involvement in uveitis development, as an increased expression was detected in iris biopsies from patients relative to controls." (PMID 35008929, 2022). "It is likely that the ICAM-1 pathway plays a fundamental role in active uveitis but in different clinical presentations of uveitis." (PMID 35008929, 2022). "ICAM-1 is a player in the pathophysiology of uveitis, a group of intraocular inflammatory diseases that may be caused by a range of infections or have autoimmune or autoinflammatory etiologies." (PMID 37237555, 2023). "ICAM-1 has been reported in several uveitis entities, particularly BD and sympathetic ophthalmia." (PMID 35008929, 2022). "ICAM-1 is also known to be involved in experimental models of uveitis." (PMID 25032222, 2014). "However, a variety of the highest-scoring interactions involved ICAM1 and IL15RA, indicating that they may be immune-mediated causes of uveitis." (PMID 36163311, 2022). "This study identified six significantly upregulated genes (CDKN1A, VCAM1, NFKBIA, ICAM1, IRF1, and CXCL10) and demonstrated that QHRGF exerts therapeutic effects on uveitis using in vivo experiments." (PMID 40718791, 2025). "As a cell adhesion molecule within cells, the intraocular fluid of uveitis patients exhibited a higher percentage of CD4+ and CD8+ lymphocytes due to ICAM-1, in comparison to the control group." (PMID 39839649, 2024). "DEG analysis unravel that cytokines, chemokines, and adhesion molecules, including ICAM-1 and VCAM-1, were highly expressed in RVECs in uveitis." (PMID 35401507, 2022). "The ICAM-1/LFA-1 and VCAM-1/VLA-4 are the main pathways reportedly involved in uveitis development in the literature." (PMID 35008929, 2022). "In murine endotoxin-induced uveitis, an acute inflammatory model, a decreased number of infiltrating leukocytes was observed in animals receiving either LFA-1- or ICAM-1-neutralizing antibodies." (PMID 36206304, 2022). "In summary, we used silibinin to inhibit TNF-α- or IFN-γ-mediated mature ICAM-1 expression in ARPE-19 cells in vitro, which is a key event in the pathogenesis of uveitis." (PMID 25032222, 2014). "A diverse array of cytokines, including IL-6, IL-4, IL-2, and IL-1, as well as intercellular adhesion molecule 1 (ICAM1), monocyte chemoattractant protein-1 (MCP-1), and tumor necrosis factor-α (TNF-α), are considered to be involved in the pathogenesis of uveitis." (PMID 39839649, 2024).
uveitis (continued). "Finally, of further interest is the identification of cell–cell interactions involving ANGPT1-TEK, ICAM1 and IL15RA which were previously attributed to glaucoma and uveitis, respectively." (PMID 36163311, 2022). "These indicated that ICAM-1/LFA-1 pathways are primarily involved in Th1-dominant uveitis, but do not have a role in cancer-associated uveitis." (PMID 35008929, 2022). "Our results suggested that GC31 suppressed LPS-mediated ICAM-1 expression by inhibiting the activation of NF-κB and partially by attenuating the activity of ERK1/2 and p38 MAPK in vascular endothelium, which may contribute to ameliorating vascular inflammatory diseases, such as uveitis." (PMID 23401649, 2013).
vasculitis (15 papers, 2012 to 2025). "To further assess systemic inflammation and potential vascular involvement, we measured plasma concentrations of intercellular adhesion molecule 1 (ICAM-1), which has been associated with vascular inflammation and vasculitis (47, –, 51)." (PMID 41159782, 2025). "In summary, we demonstrate that the horizontal transfer of platelet-derived miR-223 suppresses the expression of ICAM-1 in HCAECs, which at least in part attenuates leukocyte adhesion, thereby reducing endothelial damage in KD vasculitis." (PMID 35983051, 2022). "Here we demonstrate that KD platelet-derived miR-223 inhibits the endothelial expression of ICAM-1, at least in part contributing to attenuating the adhesion of inflammatory cells (e.g., monocytes) in KD vasculitis." (PMID 35983051, 2022). "Blockade of ICAM-1 was a well-established and highly effective treatment in vasculitis." (PMID 37228411, 2023). "Furthermore, the emergence of severe vasculitis due to HCV-associated MC was shown to be dependent on the induction of adhesion molecules including VCAM-1 and ICAM-1, both involved in mononuclear respectively polymorphonuclear and mononuclear cell recruitment during vasculitis." (PMID 25419735, 2014). "ICAM-1 and VCAM-1 are both important molecules in hyperglycemic brain injury produced by vascular instability, whether in terms of stimulating leukocyte adhesion, aggregation, or chemotaxis to cause vasculitis or the formation of cerebral atherosclerotic plaque." (PMID 40224490, 2025). "ITGB2 (CD18) a receptor for ICAM1, ICAM2, ICAM3, and ICAM4, is a potential mechanistic biomarker for vasculitis." (PMID 38274452, 2023). "The mechanism of vasculitis in EGPA appears related to increases in serum Th17 cell numbers and ICAM-1 levels and decreases in VEGF levels." (PMID 26714881, 2015). "Ucn1 stimulated IL6 expression in VSMCs and ICAM1 expression in ECs via cyclooxygenase-2, and promoted microvascular permeability during inflammation, MMP9 expression, and the development of vasculitis." (PMID 25462164, 2014). "In HO-1−/− mice, enhanced serum ICAM-1, E-selectin, and MMP-3 levels indicate the presence of vasculitis and systemic inflammation." (PMID 23285041, 2012). "Indeed, the upregulation of ICAM-1 and VCAM-1, mediated by inflammatory cytokines and cellular stress, has been related to the leukocyte-induced ED, vascular thrombosis, and disruption of vascular walls observed in childhood vasculitis and KD." (PMID 39769085, 2024).
cervical carcinoma (14 papers, 2012 to 2025). A carcinoma arising from either the exocervical squamous epithelium or the endocervical glandular epithelium. "VEGF and ICAM1 have been proven to play crucial roles in the metastasis of cervical cancer and are associated with advanced stages and recurrence of the disease." (PMID 40141137, 2025). "This study confirmed for the first time the correlation between ICAM-1 gene polymorphisms and cervical cancer in the northern Chinese Han population." (PMID 34386034, 2021). "This study focused on the relationship between the rs5498, rs3093030, and rs281432 polymorphisms of the ICAM-1 gene and the susceptibility of cervical cancer in the northern Chinese population." (PMID 34386034, 2021). "Moreover, high ICAM1 expression was associated with a worse prognosis in patients with cervical cancer." (PMID 39971940, 2025). "In conclusion, the study suggested that ICAM-1 gene polymorphisms may have a potential role in the pathogenesis of cervical cancer in the northern Chinese Han population." (PMID 34386034, 2021). "Therefore, we reported for the first time the association between ICAM-1 gene polymorphisms and the risk of cervical cancer in the northern Chinese population." (PMID 34386034, 2021). "Therefore, we aimed to explore the potential role of ICAM-1 gene polymorphisms and the combined effect of SNPs in the pathogenesis of cervical cancer in Han women in northern China." (PMID 34386034, 2021). "To determine whether alterations in the EMT is responsible for the promotion of invasion and migration caused by RSU1P2 in cervical carcinoma cells, we performed western blot assays to detect the protein levels of the epithelial marker E-cadherin and the mesenchymal markers vimentin and ICAM-1." (PMID 27487126, 2017). "These in vitro efficacy results support that two ICAM1-ADCs are potent in cervical cancer cells with high tumor selectivity, warranting further investigation in the in vivo cervical tumor models." (PMID 39971940, 2025). "To validate its clinical relativity, we queried the GEPIA database for ICAM1 expression in a total of 306 patients with cervical cancer and found that the level of ICAM1 mRNA was significantly upregulated in patients with cervical cancer." (PMID 39971940, 2025). "This study provides the inaugural experimental support for ICAM1 as a viable ADC target in cervical cancer." (PMID 39971940, 2025). "Given that cell entry is a critical factor affecting the therapeutic efficacy of ADC, we evaluated the internalization rate of ICAM1 antibodies in human cervical cancer cells." (PMID 39971940, 2025). "Further analysis, including data from clinical specimens and the GEPIA database, indicated a correlation between ICAM1 overexpression and adverse clinical outcomes in cervical cancer patients, underscoring its potential as a therapeutic target." (PMID 39971940, 2025). "Herein, we explored how ICAM1-targeted ADCs affect TAN dynamics in preclinical models of cervical cancer." (PMID 39971940, 2025). "To find the optimal ADC construct for cervical cancer therapy, we compared the antitumor efficacy of two ICAM1-ADCs of different mechanisms of action (MoAs) previously developed by us." (PMID 39971940, 2025). "We next quantified ICAM1 overexpression in human cervical cancer cells (SiHa and CaSki) by flow cytometry and immunofluorescence staining, which are 80- and 106-fold higher than those of non-neoplastic HcerEpic and 293T cells, respectively." (PMID 39971940, 2025). "The surface expression of ICAM-1 in breast and cervical cancer cell lines was selectively up-regulated by ATRA." (PMID 23300837, 2012). "Notably, immunohistochemistry and western blot assays confirmed that FN1, PLAU, and ICAM1 are significantly upregulated in cervical cancer tissues." (PMID 40141137, 2025).
cervical carcinoma (continued). "The promising synergy of I-DXd with PD-1 inhibition, suggested by enhanced CD8 + T cell recruitment and tumor suppression, alongside a comprehensive modulation of the TME, underscores the potential of ICAM1-targeted therapy to significantly advance cervical cancer treatment." (PMID 39971940, 2025). "The regulation of cellular response to the hypoxia pathway was found as the most significantly downregulated signaling pathway upon ICAM1 neutralizing antibody treatment, but further studies are needed to characterize the specific pathways activated in cervical cancer cells." (PMID 39971940, 2025). "Notably, ICAM1, an inflammation-related cell membrane protein, showed potential as a specific molecular target candidate for cervical cancer." (PMID 39971940, 2025). "Hardy–Weinberg equilibrium test results of ICAM-1 SNPs in the cervical cancer and control groups." (PMID 34386034, 2021). "Based on the findings of previous studies, there was no research on the relationship between the SNPs of the ICAM-1 gene and the risk of cervical cancer in the northern Chinese population." (PMID 34386034, 2021). "Icam1 was ranked 76th in foldchange but had the 3rd position in Venn-diaNet which also might have a E6/E7+E2 specific expression while Icam1 was also reported to have a role with HPV related cervical carcinoma." (PMID 31881980, 2019). "Many epidemiological studies have confirmed that ICAM-1 gene single-nucleotide polymorphisms (SNPs) are associated with susceptibility of various cancers, but there are relatively few studies on the relationship between ICAM-1 gene polymorphisms and the risk of cervical cancer." (PMID 34386034, 2021). "Last but not least, the relationship between the ICAM-1 gene and the risk of cervical cancer may not be achieved by affecting the structure and function of encoding protein." (PMID 34386034, 2021). "Our investigation has yielded two promising ICAM1-targeted ADCs (I-DXd and I-MMAE) that have demonstrated preclinical efficacy and safety in models of cervical cancer." (PMID 39971940, 2025). "We next determined the in vitro cytotoxicity of two ICAM1-ADC constructs in a panel of cervical cancer (SiHa and CaSki) and non-neoplastic (HcerEpic and 293T) cell lines." (PMID 39971940, 2025). "By employing an unbiased and quantitative approach, we identified ICAM1 as a membrane protein that is overexpressed in cervical cancer cells but not in adjacent normal cervical epithelia." (PMID 39971940, 2025).
dry eye (14 papers, 2009 to 2025). "LF inhibits the interaction between intercellular adhesion molecule 1 (ICAM-1) and lymphocyte function-associated antigen 1 (LFA-1), targeting the inflammatory cycle central to dry eye." (PMID 39861101, 2025). "A mouse desiccating dry eye model showed beneficial effects by blocking the interaction between LFA-1 (Lymphocyte function-associated antigen 1; CD11a) and ICAM-1 (Intercellular Adhesion Molecule 1; CD54)." (PMID 33467204, 2021). "Long-term dry eye is associated with increased expression of inflammatory factors, such as TNF-α, MMP-2, MMP-9, ICAM-1, and VCAM-1, on the ocular surface." (PMID 30002412, 2018). "Conjunctival epithelium expression of HLA-DR (human leukocyte antigen-DR) and ICAM-1 (intercellular adhesion molecule-1) have been shown to be correlated with some topical inflammatory processes like allergic conjunctivitis, pterygium, or keratoconjunctivitis sicca (KCS) in cystic fibrosis." (PMID 24562464, 2014). "Long-term dry eye is associated with increased expression of inflammatory factors, such as tumor necrosis factor-alpha (TNF-α), matrix metalloproteinase (MMP-2, MMP-9), intercellular adhesion molecule-1 (ICAM-1), and vascular cell adhesion molecule-1 (VCAM-1) in the ocular surface." (PMID 30002412, 2018). "ICAM-1, an adhesion molecule that recruited and assisted in the migration of inflammatory cells during inflammation response of DED, has been a target for dry eye therapy." (PMID 35223927, 2022). "In a murine model of the autoimmune-mediated dry eye characteristic of SS, the male Non-Obese Diabetic NOD mouse, ICAM-1 is highly expressed in the LG, both in LG acinar cells (LGAC) and in infiltrating immune cells." (PMID 32326657, 2020). "This is in agreement with previous studies in symptomatic, moderate dry eye patients, where there were no increases in levels of IL-1β, IL-6, IL-8/CXCL8, GRO-b, ICAM-1, TRAIL, or ephrin A5 in tear fluid." (PMID 20508732, 2010).
lung disease (14 papers, 2006 to 2025). "There is also potential to combine anti-ICAM-1 therapies with anti-PAFr therapies, that could theoretically then prevent both viral and secondary bacterial infections in highly susceptible lung disease patients." (PMID 35316427, 2022). "ICAM-1 is a type of adhesion molecule that is thought to mediate monocyte binding to epithelial cells during the development of pulmonary diseases." (PMID 29329563, 2018). "Elevated plasma or serum concentrations of soluble ICAM-1 (sICAM-1) have been reported in patients with pulmonary diseases." (PMID 29329563, 2018). "Casticin also can suppress ICAM-1 expression, decrease eosinophil migration into lung epithelial cells, and attenuate the acute lung inflammatory response in cigarette smoke–induced lung disease in mice." (PMID 29254155, 2017). "Similarly, elevated levels of soluble VCAM-1, E-selectin, and ICAM-1 have been found in patients with SSc renal crisis, but not in those with SSc-associated pulmonary disease." (PMID 40094867, 2025). "Since ICAM-1 expression is upregulated in inflammation-associated lung diseases, and cross-linking ICAM-1 on airway epithelial activated ERK and JNK in vitro, we further investigated whether ICAM-1 cross-linking altered the expression of the pro-inflammatory chemokines RANTES and IL-8." (PMID 16430772, 2006). "In our study, this pathway was significantly extracted from general SSc (upregulated proteins) and lung disease related to SSc (downregulated proteins) subgroups (ITGB1;ACTN1;ICAM1;ITGAM;MMP9)." (PMID 36732374, 2023). "However, only modestly increased levels of ICAM-1 and ICAM-2 expression were found on inflamed bronchial epithelium from patients with COPD (another lung disease characterized with neutrophilic-driven inflammation) compared to normal lung." (PMID 34484188, 2021). "By contrast, lung disease in MRLlpr mice involves the recruitment of CXCR3 positive T cells via local secretion of CXCL10, and the endothelial expression of selectins and intercellular adhesion molecule (ICAM)-1." (PMID 21637713, 2011).